RNU1-103P (RNA, U1 small nuclear 103, pseudogene)
Gene: Small nuclear RNA gene on chromosome 16 (85,781,775 to 85,781,899, reverse strand). Ensembl gene ENSG00000252311.
Homologues: Orthologues: macaque U1 (90% identical), pig U1 (78% identical), dog U1 (76% identical), rabbit U1 (75% identical), guinea pig U1 (74% identical), mouse Gm23303 (72% identical), rat U1 (65% identical). Paralogues in human: RNU1-89P (82% identical), RNU1-1 (82% identical), RNU1-2 (82% identical), RNU1-27P (82% identical), RNU1-28P (82% identical), RNU1-3 (82% identical), RNU1-4 (82% identical), RNVU1-18 (82% identical), RNVU1-29 (82% identical), RNVU1-7 (82% identical), U1 (82% identical), RNU1-39P (81% identical), and 134 more.